NLRP3 (NLR family pyrin domain containing 3)
Diseases named in the same sentence as NLRP3 in open-access papers (continued):
Sharing a sentence is not in itself a finding about the gene and the disease.
Stroke (continued). "Considering the essential role of oxidative stress in the activation of NLRP3 inflammasome and in mediating the pathogenesis process of neurological diseases such as stroke, not surprisingly, it has become a hot topic of research." (PMID 36160384, 2022). "Furthermore, NLRP3 inflammasome activation has been reported in cerebral ischemia/reperfusion injury (CIRI) models, as well as in stroke patients." (PMID 35836200, 2022). "A study found that AIM2 inflammasomes contributed to ASC to acute brain injury independent of NLRP3 after stroke." (PMID 35401398, 2022). "The immunofluorescent staining results showed that NLRP3+ positive cells were increased at 3 days but gradually decreased from 7 to 14 days following stroke in animals without apocynin." (PMID 35836200, 2022). "Compared with patients without MBE, those with MBE had higher levels of serum concentration of NLRP3 on admission (median concentration 1.85 [IQR 0.98–3.87] ng/ml vs. 1.11 [0.94–2.44] ng/ml, P = 0.026; median time from the onset of stroke to blood sample collection 3 h, IQR 2-4 h)." (PMID 34493232, 2021). "Even though majority of the studies are centered around the NLRP3 inflammasome and its role in stroke pathophysiology, multiple other inflammasome constituents have been addressed in inflammatory responses of the NVU related to stroke." (PMID 32635451, 2020). "Although NLRP3 gradually increased over the 24 h after MCAO, NLRP3 was continuously colocalized with Iba-1–positive microglia (>80%) during this period, indicating that NLRP3 was primarily activated in the microglia after stroke." (PMID 32625078, 2020). "Some studies reported the neuronal increase of NLRP3 at the third day after stroke, but some demonstrated no expression within 24 h." (PMID 32625078, 2020). "Finally, an expression analysis in the peri‐infarct zone of transient MCAO rats revealed elevated levels of the inflammasome components NLRP1, NLRP3, AIM2, NLRC4, and ASC, consistent with the potential activation of multiple inflammasomes in stroke." (PMID 31015277, 2019). "Congruently, we have previously shown that infarct size following the intraluminal filament MCAO model of stroke is equivalent in OPN-/- and WT mice, however, NLRP3-/- and CD36-/- mice have been reported to have smaller infarct volumes compared to WT mice following intraluminal filament MCAO." (PMID 30417081, 2018). "Moreover, previous reports have demonstrated that TXNIP expression is upregulated in brain tissue after stroke in animals, and ROS induces the dissociation of TXNIP and actives NLRP3." (PMID 27589720, 2016). "Although NLRP3 plays a significant role in post-stroke inflammation, there may be some residual protection even in the absence of NLRP3 due to compensatory pathways such as IL- 10/Jak-Stat stabilization and other inflammasomes like AIM2 and NLRC4." (PMID 40272769, 2025). "The current study found that pre-treatment with the KG diet decreased the production of ROS following stroke and could lower the activation of the TXNIP/NLRP3 inflammasome, suggesting that the KG diet may protect brain damage from ROS-mediated NLRP3 activation." (PMID 40272769, 2025). "Both the inhibition of AIM2 and NLRP3 prevented inflammasome activation in the CCA plaque after stroke, with greater efficacy of the AIM2 inhibitor, whereas only the AIM2 inhibitor significantly prevented the post-stroke increase in IL-1β levels in the CCA plaque." (PMID 39112714, 2024). "Therefore, NLRP3 may provide an alternative therapeutic target to mitigate the detrimental effect of CMI and subsequent stroke." (PMID 38216560, 2024). "CY-09 inhibits NLRP3 activation by binding to the Walker A motif of NLRP3 and reducing NLRP3 binding to ATP; similar to MCC950, it inhibits NLRP3-dependent inflammatory diseases and could be a potential drug for the treatment of stroke." (PMID 37165005, 2023).
Stroke (continued). "In the process amplified NLRP3 activation was observed, and NLRP3 inhibitor could ameliorate cognitive function and vascular integrity in a high-fat diet/streptozotocin-induced (HFD/STZ) diabetic male Wistar rat model with stroke." (PMID 37332874, 2023). "Unlike in arterial ischemia, where NLRP3 changes suddenly minutes to hours after stroke onset, NLRP3 in CVT activates in a subacute fashion, evident at day 3, and maintained until day 7 after CVT, which is in parallel with the immune cell activation and infiltration." (PMID 35444662, 2022). "Moreover, we found that besides NLRP3, other receptors, such as NLRC4, participated in post-stroke inflammasome formation in mice models, which indicates that NLRP3 is not the only path for inflammasome activation." (PMID 33967935, 2021). "We further proposed the viewpoint that hippocampal inflammatory response activation followed by stroke could play a crucial role in the pathogenesis of PSD and that alleviating hippocampal inflammation through downregulating NLRP3 inflammasome is a potential novel target for PSD." (PMID 34559953, 2021). "Nevertheless, no expression alteration of NLRP3 level was detected in patients, which revealed that the function of NLRP3 might be negligible in post-stroke inflammasome activation." (PMID 33967935, 2021). "The depletion of NLRP3 failed to display any beneficial effects after stroke in this study." (PMID 32645874, 2020). "In accordance with Stroke Treatment Academic Industry Roundtable (STAIR) suggestion for rigorous preclinical research and to consider large vessels occlusion models, our experimental findings show specific NLRP3 inhibition with MCC950 protect the brain against MCAO in mice." (PMID 29654318, 2018). "In addition, Denes and colleagues highlighted the adaptor molecule, ASC, as being a crucial regulator in the inflammatory response after stroke, whereas inhibition of the other components that form the NLRP3 inflammasome complex did not improve stroke outcome." (PMID 26690125, 2015). "Our results demonstrated that, compared with those in the sham group, the mRNA levels of AIM2 and NLRP3, but not those of NLRP1a and NLRC4, were significantly elevated following stroke." (PMID 39854137, 2025). "Aerobic exercise is a potent non-pharmacological intervention for post-stroke cognitive recovery, exerting benefits through synergistic mechanisms: enhanced cerebral perfusion, BDNF-driven neuroplasticity and NLRP3 inflammasome suppression." (PMID 40256392, 2025). "Although this study found that the improvement of stroke by acupuncture was related to the upregulation of SIRT1 expression levels in brain tissue and the significant downregulation of the expression levels of NLRP3 and IL-18, the specific in-depth mechanisms were not further studied." (PMID 36059399, 2022).
inflammatory bowel disease (191 papers, 2013 to 2026). A spectrum of small and large bowel inflammatory diseases of unknown etiology. "Recent investigations have underscored the pivotal role of unchecked NLRP3 inflammasome activation in the development of inflammatory bowel disease, with heightened secretion of mature IL-1β and IL-18 linked to exacerbated colitis." (PMID 40640149, 2025). "A recent study of very-early-onset inflammatory bowel disease (VEO-IBD) patients identified an NLRP3 variant (R779C) in three patients which resulted in increased inflammasome activation and cytokine release." (PMID 38763335, 2024). "The NLRP3 inflammasome plays a pivotal role in the onset and progression of inflammatory bowel disease and is also implicated in colorectal cancer." (PMID 39519191, 2024). "It’s important to note that improper activation of the NLRP3 inflammasome is linked to various conditions, ranging from Inflammatory Bowel Disease (IBD) to acute myocardial infarctions." (PMID 38162646, 2023). "The gut mucosa disruption is a hallmark of inflammatory bowel diseases (IBD) characterized by an upregulated NLRP3 inflammasome pathway, which can be triggered following short chain fatty acids (SCFAs) binding to GPR43 of the enterocytes." (PMID 37743919, 2023). "NLRP3 inflammasome is closely associated with the progression of multiple diseases, such as Hp gastritis, gastric cancer, and inflammatory bowel disease." (PMID 36597090, 2023). "Inflammatory bowel disease (IBD) has been reported to be associated with NLRP3 inflammasome activation." (PMID 35784693, 2022). "Recently, it has been found that the aberrant activation of NLRP3 inflammasome is associated with a variety of diseases, such as metabolic syndrome, neuroinflammation, and inflammatory bowel disease (IBD)." (PMID 35252186, 2022). "It is worthwhile to test the effect of CS on other NLRP3-associated disease models in the future, such as inflammatory bowel disease and Huntington’s disease." (PMID 35669789, 2022). "Previous studies have reported association between NLRP3 genetic variants and risk of inflammatory conditions such as rheumatoid arthritis and inflammatory bowel diseases." (PMID 36238294, 2022). "Experimental animal studies have linked NLRP3 inflammasome activation to inflammatory bowel diseases." (PMID 34630405, 2021). "The activity of multiple inflammasomes has been implicated in inflammatory bowel disease in the regulation of commensal microbiota, while NLRP3, NLRP6, and NLRC4 expression can influence tumor formation." (PMID 34903717, 2021). "As abnormal activation of the NLRP3 inflammasome leads to a broad range of inflammatory disorders, F240B has the potential to ameliorate NLRP3-associated diseases, including chronic kidney disease, inflammatory bowel disease and neurodegenerative disorders." (PMID 33424855, 2020). "Intestinal inflammation in moderate to severe pathology associated with inflammatory bowel disease phenotypes show consistent infiltration of leukocytes and NLRP3-inflammasome activation." (PMID 31217465, 2019). "It has been inconsistently associated with other auto-inflammatory phenotypes, with some evidence for epistatic interaction with NLRP3 rs35829419 in determining risk of inflammatory bowel disease and abdominal aortic aneurysms." (PMID 26462562, 2015). "The authors hypothesize that the R779C variant lowers the threshold for NLRP3 activation by maintaining a low ubiquitination state, ultimately contributing to the severe inflammatory bowel disease seen in these patients." (PMID 38763335, 2024). "Second, since the NLRP3 inflammasome is associated with inflammatory bowel disease, NLRP3 inflammasome inhibition by ezetimibe treatment could attenuate inflammation in the gut, stabilising the gut microbiome that helps absorb choline." (PMID 35740238, 2022).
inflammatory bowel disease (continued). "Recently, an increasing number of evidence showed that NLRP3 inflammasome is associated with many diseases, including cardiovascular diseases, inflammatory issues (such as liver diseases and inflammatory bowel diseases), neurologic disorders, endometriosis and pseudomonas aeruginosa infection." (PMID 34123595, 2021). "We recently have proved that excessive fecal DCA caused by high-fat diet may serve as an endogenous danger-associated molecular pattern to activate NLRP3 inflammasome and thus contributes to the development of inflammatory bowel disease (IBD)." (PMID 29854830, 2018). "The NLRP3 inflammasome is associated with onset and progression of various diseases, including metabolic disorders, multiple sclerosis, inflammatory bowel disease, cryopyrin-associated periodic fever syndrome, as well as other auto-immune and auto-inflammatory diseases." (PMID 26594174, 2015). "Inflammatory bowel disease (IBD) is triggered by genetic predisposition and chronic inflammation, with aberrant activation of the innate immune complex NLRP3 inflammasome playing a pivotal role in its pathogenesis." (PMID 41898537, 2026). "Ginger-derived VLNs (Gg-DVLNs) suppress NLRP3 inflammasome activity, reducing inflammation linked to inflammatory bowel disease (IBD)." (PMID 40867501, 2025). "Previous studies have demonstrated that NLRP3 is associated with susceptibility to inflammatory bowel disease (IBD) while also regulating intestinal homeostasis through control over intestinal epithelial integrity, microbiota composition, and immune response." (PMID 39355844, 2024). "The inflammatory cytokine tumor necrosis factor alpha (TNFα) induces the assembly of the NLRP3 inflammasome, resulting in the augmented secretion of inflammatory cytokines implicated in the pathogenesis of inflammatory bowel disease (IBD)." (PMID 38667290, 2024). "Inappropriate NLRP3 inflammasome activation is also implicated in Crohn's disease, inflammatory bowel disease (IBD), and ulcerative colitis." (PMID 31749805, 2019). "Human inflammatory bowel disease (IBD) is a common chronic and recurrent inflammation, and increasing evidence supports that the NLRP3 inflammasome is implicated in the development of IBD." (PMID 28978034, 2017). "While no SNP in the NLRP3 region is directly associated with inflammatory bowel disease (IBD), a SNP downstream of NLRP3 has been previously identified as a risk allele in Crohn’s disease." (PMID 24137163, 2013). "NLRP3 plays an important function in anti-infection immunity and contributes to inflammatory conditions, including inflammatory bowel disease (IBD) and other immune-related intestinal disorders." (PMID 41149694, 2025). "Further research is necessary to clarify the NLRP3 inflammasome’s mechanisms in inflammatory bowel diseases." (PMID 40362256, 2025). "Although NLRP3 inflammasome activation and impaired autophagy are linked to inflammatory bowel disease (IBD), the underlying mechanisms remain unclear." (PMID 39899477, 2025). "Activation of inflammasomes particularly NLRP3 and NLRP1, plays central role in driving inflammatory response associated with inflammatory bowel disease (IBD)." (PMID 41129928, 2025). "The inflammasome behaves differently during disease progression; normally, NLRP3 is minimally expressed, but inflammatory bowel disease triggers increased cellular permeability and intestinal mucosa damage, activating the inflammasome." (PMID 40362256, 2025). "For example, hypomethylation of the NLRP3 promoter has been observed in patients with inflammatory bowel disease (IBD), leading to enhanced expression of NLRP3 and increased inflammation." (PMID 40046056, 2025). "While the primary focus of this review is asthma, it is important to note that dysregulated NLRP3 activity is also implicated in other chronic inflammatory diseases, particularly juvenile idiopathic arthritis (JIA) and inflammatory bowel disease (IBD)." (PMID 41318536, 2025).
inflammatory bowel disease (continued). "Transcriptomic analysis revealed 307 differentially expressed genes were decreased in Nlrp3-/- mice compared with control mice, which was related to humoral immune response, complement activation, phagocytic recognition, malaria and inflammatory bowel disease." (PMID 38756775, 2024). "The analysis of KEGG enrichment pathways suggest that Nlrp3 is closely related to malaria, inflammatory bowel disease, type 1 diabetes, JAK-STAT signaling pathway, etc. in DH." (PMID 38756775, 2024). "It decreases proinflammatory cytokines, thereby attenuating inflammatory bowel disease by targeting and downregulating the pyroptotic protein, NLR family pyrin domain containing 3 (NLRP3)." (PMID 38892270, 2024). "Reduced expression of NLRP3 has been observed in JSpA and it is proposed that this contributes to permeability of the gut and subclinical inflammation which is seen in studies with defective NLRP3 inflammasome signaling (i.e., inflammatory bowel disease)." (PMID 37598797, 2023). "Research into the dual roles of NLRP3 inflammasomes in autoinflammatory syndromes has been a focal point for over a decade, yet their exact role in conditions like inflammatory bowel diseases remains elusive." (PMID 38162646, 2023). "Studies regarding the use of medicinal plants with regulatory effects on NLRP3 inflammasome in inflammatory bowel diseases." (PMID 37367886, 2023). "It has been shown that NEK7 (mitotic kinase) interacts with NLRP3 to regulate pyroptosis in inflammatory bowel disease (IBD) through the NF-κB signaling pathway." (PMID 37821972, 2023). "For example, NEK7 regulates the activation of NLRP3 inflammasome and the subsequent pyroptosis through the interaction between NEK7 and NLRP3, thus influencing the advancement of inflammatory bowel disease." (PMID 37506161, 2023). "NEK7 was found to modulate the pyroptosis of MODE-K cells by interacting with NLRP3 in an inflammatory bowel disease (IBD) model." (PMID 36177039, 2022). "NEK7 has been reported to be interacted with NLRP3 to modulate the pyroptosis in inflammatory bowel disease via NF-κB signaling." (PMID 35991122, 2022). "The NLRP3 inflammasome has reportedly been implicated in the pathogenesis of various diseases, including autoimmune diseases such as RA, inflammatory bowel disease (IBD), multiple sclerosis (MS), and type I diabetes." (PMID 34379187, 2022). "Inflammatory bowel disease, a complex inflammatory disorder, can be relieved by huc-MSCs-derived exosomes, which inhibit NLRP3 inflammasomes and cell pyroptosis through transferring miR-378a-5p." (PMID 35836229, 2022). "NLRP3 inflammasome is implicated in the pathogenesis of inflammatory bowel diseases (IBD)." (PMID 35722277, 2022). "Recent studies have shown that NLRP3 is involved in maintaining the stability of the intestinal environment and is also closely related to the occurrence and development of inflammatory bowel disease." (PMID 33505499, 2021). "NF κB signal was reported to modulate NLRP3 inflammasome-induced pyroptosis in adipose inflammation and inflammatory bowel disease." (PMID 33679744, 2021). "In addition, NLRP3 has been implicated in several other diseases including inflammatory bowel disease (IBD), rheumatoid arthritis, and Parkinson's disease." (PMID 32733479, 2020). "In particular, the NOD-like receptor protein 3 (NLRP3) inflammasome plays crucial roles in host defense against infection, inflammation-induced cancer, and several inflammatory diseases including inflammatory bowel disease." (PMID 32435622, 2020). "Increasing evidences indicated that the dysregulation of NLRP3 inflammasome plays a critical role in the pathogenesis of several inflammatory diseases, such as atypical dermatitis, inflammatory bowel disease and neurodegenerative diseases." (PMID 32754591, 2020). "The NOD-like receptor protein 3 (NLRP3) inflammasome plays a key role in the progression of inflammatory bowel disease and CAC." (PMID 32435622, 2020).